CLUL1 (clusterin like 1)
Synonyms: RA337M
Tractability: Antibody: UniProt places it where antibodies can reach, with high confidence; UniProt predicts a signal peptide or a membrane-spanning region; its Gene Ontology location is reachable by antibodies, with medium confidence; the Human Protein Atlas places it where antibodies can reach.
Gene: Protein-coding gene on chromosome 18 (596,988 to 650,334, forward strand). Ensembl gene ENSG00000079101.
Subcellular location: Secreted
Subcellular location (Human Protein Atlas): Endoplasmic reticulum; Plasma membrane; Predicted to be secreted
Gene Ontology:
Molecular function: misfolded protein binding
Cellular component: nucleus; extracellular region
Genetic constraint (gnomAD): Loss-of-function variants: 39 observed, 47.85 expected, observed/expected ratio (o/e) 0.82, 90% interval 0.63 to 1.07. The upper end of that interval is the gene's LOEUF score, 1.07, which puts it in group 4 of 6, group 1 being the genes least tolerant of losing a copy. Missense variants: 483 observed, 565.86 expected, observed/expected ratio (o/e) 0.85, 90% interval 0.79 to 0.92. Synonymous variants: 191 observed, 194.27 expected, observed/expected ratio (o/e) 0.98, 90% interval 0.87 to 1.11.
Homologues: Orthologues: chimpanzee CLUL1 (98% identical), macaque CLUL1 (95% identical), dog CLUL1 (73% identical), pig CLUL1 (73% identical), rabbit CLUL1 (71% identical), guinea pig CLUL1 (67% identical), rat Clul1 (61% identical), tropical clawed frog clul1 (32% identical), zebrafish clul1 (30% identical). Paralogues in human: CLU (24% identical).
Diseases named in the same sentence as CLUL1 in open-access papers:
CLUL1 is named in the same sentence as 10 diseases in open-access papers, as found by Europe PMC text mining. Sharing a sentence is not in itself a finding about the gene and the disease. The quoted sentences say what the papers report.
retinoblastoma (3 papers, 2021 to 2024). A malignant tumor that originates in the nuclear layer of the retina. "We have successfully identified a few gene signature (CLUL1, CNGB1, ROM1 and RDH12) to predict the risk of invasion in retinoblastoma and therefore, in this study, we investigated the profiles of invasive risk panel between subtypes." (PMID 37777551, 2023). "Interestingly, the retinoblastoma invasion markers (CLUL1, CNGB1, ROM1 and RDH12) were predominantly higher in subtype 1b, suggesting subtype 1b retinoblastoma prone to be more invasive as compared with other subtypes." (PMID 37777551, 2023). "It has been reported that CLUL1, CNGB1, ROM1, LRRC39, and RDH12 genes in different retinoblastoma subtypes are involved in the progression and development of the disease, which can be useful as biomarkers (M.)." (PMID 34646884, 2021).
myopia (2 papers, 2011 to 2024). "Surprisingly, genes associated with retinal disorders (CLUL1, VSX1, RD3, RS1, and CABP4) and a cone pigment (OPN1LW) were identified in choroid but not retina of progressing chick myopia." (PMID 39028695, 2024).
macrosomia (1 paper, 2023). "The 9 indicators verified by nomogram in this analysis, including pre-pregnancy BMI, weight gain at 24 gw, parity, OGTT 2 h glucose at 24 gw, HDL and LDL at 24 gw, and plasma expression of CLUL1, VCAN and RNASE3 at 24 gw, are very meaningful in terms of identifying macrosomia risk in GDM." (PMID 36788507, 2023). "The Model included pre-pregnancy BMI, weight gain at 24 gw, parity, OGTT 2 h glucose at 24 gw, HDL and LDL at 24 gw, and plasma expression of CLUL1, VCAN and RNASE3 at 24 gw had good prediction performance for predicting macrosomia in women with GDM." (PMID 36788507, 2023).
retinal diseases (1 paper, 2018). "Based on its developmental regulation, distinct localization, and possible involvement in a wide range of cellular retinal processes, CLUL1 represents a potential candidate for retinal diseases, particularly those that affect cones." (PMID 29529059, 2018).
visual disorders (1 paper, 2024). "Moreover, high disease risk scores of rods with visual disorders imply that TS has great potential to mimic rod-related diseases such as RP, CSNB, and LCA; furthermore, the mechanistic role of CLUL1 in rod-related deficits requires further investigation." (PMID 39574940, 2024).
CLUL1 also shares sentences with these, for which no sentence is quoted: cancer (1 paper); clear cell renal cell carcinoma (1); microphthalmia (1); neoplasm (1); retinal disorder (1).